GLI1 (GLI family zinc finger 1)
Diseases named in the same sentence as GLI1 in open-access papers (continued):
Sharing a sentence is not in itself a finding about the gene and the disease.
ovarian carcinoma (continued). "In addition, when ovarian cancer cells are treated with a hedgehog inhibitor, cyclopamine, and Gli1 siRNA, the anoikis resistance can be significantly reduced, substantiating that Gli1 is a key protein in the induction of anoikis in ovarian cancer." (PMID 36104717, 2022). "Interestingly, low SPOP levels contributed to enhanced Hh signaling by modulating GLI1/2 expression, resulting in decreased apoptosis in ovarian cancer cell lines." (PMID 34572373, 2021). "Additionally, there is higher expression of SMO and Gli1 in borderline and malignant tumor tissues than in benign tumor and normal ovarian tissues, indicating their importance in progression of ovarian cancer." (PMID 32776013, 2020). "GLI1 also shown co-expression within breast, lung and ovarian cancer datasets." (PMID 31973134, 2020). "Targeting GLI1 may improve clinical benefits in the chemotherapy-exacerbated metastasis in ovarian cancer treatment." (PMID 32242101, 2020). "Gli1 is a regulator of proliferation and tumor growth in ovarian cancer." (PMID 30042330, 2018). "Gli1 antagonists such as HPI 1–4 that are currently being developed as well as drugs targeting PTCH may be useful therapies for ovarian cancer patients with activated Hh signaling." (PMID 30042330, 2018). "In ovarian cancer, Gli1 appears to be a critical contributor." (PMID 30042330, 2018). "This suggests that Gli1 regulates DNA adduct repair and sensitivity to cisplatin in ovarian cancer." (PMID 30042330, 2018). "Using DYRK1B-amplified pancreatic and ovarian cancer cells, co-targeting both kinases resulted in a significantly reduced GLI1 level and in increased cell death induction which could help to design new cancer therapies in the future." (PMID 27903983, 2017). "Similarly, shRNA-mediated downregulation of GLI1 in ovarian cancer cells resulted in sensitizing these cells to cisplatin; reducing the IC50 value from 30 μM to 5 μM." (PMID 26633513, 2015). "Furthermore, GLI1 downregulated ovarian cancer cells treated with cisplatin showed a switch in the phosphorylation pattern of c-JUN from Ser63/73 to Thr91/93." (PMID 26633513, 2015). "In the present study, we explore whether inhibition of Gli1 has any effect on total cellular accumulation of cisplatin in A2780-CP70 cisplatin-resistant human ovarian cancer cells." (PMID 24926795, 2014). "Here we investigated the role of the transcription factor Gli1 in ovarian cancer." (PMID 23555905, 2013). "In addition, ectopic Gli1 overexpression in ovarian cancer cells increased cell proliferation, cell mobility, invasiveness and induced differentiation, identifying Gli1 expression as an independent prognostic marker." (PMID 23303278, 2013). "Silencing Gli1 expression induced anoikis in the examined ovarian cancer cells." (PMID 23303278, 2013). "Moreover, compared to a control epithelial cell line, ovarian cancer cell lines demonstrated significant activation of the Hh pathway, determined by increased expression of intranuclear Gli1." (PMID 23303278, 2013). "In ovarian carcinoma, GLI1 was reported to regulate the growth of CSCs." (PMID 23285037, 2012). "Moreover, ectopic expression of Gli1 in ovarian cancer cells resulted in increased cell proliferation, mobility and invasive properties." (PMID 22140510, 2011). "Finally, we addressed whether the LPA-promoted signature associated with Hh (GLI1, BMI1) and EMT (SNAI1, TWIST1) genes has an impact on the clinical outcome of ovarian cancer patients." (PMID 34831435, 2021). "The inhibition of GLI1 following chemotherapy may serve as a novel strategy to ensure the crucial killing effect of chemotherapy on tumour cells and inhibit the chemotherapy-exacerbated metastasis in ovarian cancer treatment." (PMID 32242101, 2020). "We analyzed the mRNA expression profiles of HH-related genes—SHH, HHAT, PTCH1, GLI1, GLI2, GLI3, and SUFU—in two ovarian cancer cell lines." (PMID 40565349, 2025).
ovarian carcinoma (continued). "Hedgehog signaling has been reported to regulate expression of ABC transporters in ovarian epithelial cancer, and STIL, being a positive regulator of GLI1-mediated hedgehog regulation, was found to be significantly regulating side population in CRC cells." (PMID 34485108, 2021). "Follow-up functional experiments illustrated that inhibiting GLI1 reversed the chemotherapy-exacerbated CSC-like traits, including CD44 and CD133, as well as prevented the migration of ovarian cancer cells." (PMID 32242101, 2020). "Downregulation of GLI1 reversed the chemotherapy-induced CSC-like characteristics and migration of ovarian cancer cells." (PMID 32242101, 2020). "Activation of PI3K-AKT signaling has been found to enhance GLI1 protein stability in pancreatic and ovarian cancer and in anaplastic large cell lymphoma (ALCL), where AKT1 counteracts the inhibitory effect of GSK3β on GLI1." (PMID 31244888, 2019). "Inhibition of Gli1 decreases ABCB1 and ABCG2 gene expression in ovarian cancer and enhances ovarian cancer-specific chemotherapeutic response." (PMID 29117122, 2017). "It was recently found that abnormal expression of the hedgehog (Hh) signaling pathway transcription factor Gli1 is involved in the regulation of ABC transporters ABCB1 and ABCG2 in ovarian cancer." (PMID 26649310, 2015). "It was found that the inhibition of Gli1 expression can decrease ABCB1 and ABCG2 gene expression levels and enhance the response of ovarian cancer cells to specific chemotherapeutics." (PMID 26649310, 2015). "Using a Gli1-specific shRNA, we explored the role of Gli1 in the cellular accumulation and efflux of cisplatin, in cisplatin-resistant A2780-CP70 human ovarian cancer cells." (PMID 24926795, 2014). "The effect of bortezomib on hedgehog transcriptional activity (as determined by PTCH1, GLI1, GLI2 gene expression) in SKOV3TRip2 cells led us to evaluate this compound in other ovarian cancer cell lines." (PMID 25216523, 2014). "Using the database Kaplan–Meier plotter, which includes the gene expression and survival data of 1565 ovarian cancer patients, higher expression levels of the genes SHH, PTCH1, PTCH2, and GLI1 displayed better survival correlations, while GLI, GLI3, and SUFU correlated with adverse outcomes." (PMID 40565349, 2025). "To assess their potential prognostic value, we analyzed the correlation between the expression levels of the following eight components of the Hedgehog signaling pathway on the progression-free (PFS) and overall survival (OS) in ovarian cancer: SHH, GLI1, GLI2, GLI3, PTCH1, PTCH2, HHAT, and SUFU." (PMID 40565349, 2025). "Similarly, GLI1 knockdown resulted in significant downregulation of ABCG2 in OVCAR3 and A2780 ovarian cancer cell lines." (PMID 37954979, 2023). "Downregulation of Jagged1 in drug resistant ovarian cancer cell line SKOV3TRip2 did not alter ABCB1 mRNA, but resulted in diminished GLI2 (Glioma-associated oncogene homolog 2), although not GLI1." (PMID 35582031, 2021). "Gli1 has also been found to play a role in expression of ABC transporters ABCG1 and ABCG2 by directly binding to their promoter regions resulting in increased resistance to both cisplatin and paclitaxel in spheroid forming of ovarian cancer cells." (PMID 32776013, 2020). "To elucidate whether DHA exerted anti‐ovarian cancer effects via inhibiting the hedgehog pathway, we explored the effects of DHA on expression of Shh, Ptch1, Smo, and GLI1 following treatment with DHA for 48 hours." (PMID 30338663, 2018). "Further analysis revealed that this particular 130-kDa isoform of GLI1 is expressed only in the ovarian cancer cells and not in normal ovarian cells." (PMID 26633513, 2015). "Moreover, Gli1 and SMO were highly overexpressed in platinum-resistant ovarian cancer." (PMID 30042330, 2018). "Thus, the 130-kDa GLI1 isoform is more highly expressed in ovarian cancer, as opposed to non-cancer ovarian tissues." (PMID 24366538, 2014).
ovarian carcinoma (continued). "Unfortunately, owing to the limited stroma component usually associated with high-grade lesions, we were not able to determine the extent of Gli1 expression in tumor microenvironment, and more studies are needed to better clarify the role of paracrine Hh signaling in ovarian cancer." (PMID 23555905, 2013). "In order to confirm the lack of effect of Hh pathway modulation on ovarian cancer cell proliferation, A2780, SKOV-3 and OVCAR-3 were exposed to increasing concentration of GANT58, a specific Gli1 inhibitor." (PMID 23555905, 2013). "Most tumors with elevated expression of Gli1 and PTCH1 had no expression of SMO, suggesting that SMO expression was not responsible for hedgehog signaling activation in ovarian cancer." (PMID 19943941, 2009).
lung cancer (43 papers, 2009 to 2025). A malignant neoplasm involving the lung. "Reports have associated GLI-1 with enhanced proliferation, inhibition of apoptosis, metastasis, poor survival outcomes, and chemoresistance in lung cancer." (PMID 39971779, 2025). "The sonic hedgehog (SHH) cascade and its key terminal factor, glioma-associated oncogene homolog 1 (GLI1), play a pivotal role in the stemness and drug resistance of lung cancer." (PMID 37149646, 2023). "Lung cancer patients tissues illustrated positive associations between Gli1 and EMT markers, including N-cadherin and Vimentin, both of which are associated with increased EMT." (PMID 31931858, 2020). "Pharmacological intervention of GLI1 to block signaling transduction may reverse the stemness-associated malignant features of lung cancer cells." (PMID 37149646, 2023). "Overexpression of GLI1 has been reported in multiple solid tumor types, including medulloblastoma, rhabdomyosarcoma, biliary, breast cancer, prostate cancer colon cancer, bladder cancer, and lung cancer, and is also associated with metastatic tumors." (PMID 31783569, 2019). "Overall, these results suggest that MEOX2 and GLI-1 play divergent roles in lung cancer progression, and response to EGFR-TKIs-based therapy, with both MEOX2/GLI-1 potentially influencing EGFR gene expression." (PMID 39971779, 2025). "Conversely, the shGLI-1 group showed increased tumor size, which contradicts previous studies where GLI-1 has been shown to promote proliferation and tumor growth in lung cancer." (PMID 39971779, 2025). "Lung cancer remains the leading cause of cancer-related mortality globally, with genes such as SMARCB1, MEOX2, and GLI-1 playing significant roles in its malignancy." (PMID 39971779, 2025). "To assess the clinical significance of MEOX2 and GLI-1 expression in lung cancer, we analyzed the TCGA Lung Cancer dataset, focusing on PFI curves in early-stage patients." (PMID 39971779, 2025). "Indicating how MEOX2 and GLI-1 regulate the abundance of oncogenic and epigenetic markers through lung cancer in vivo progression, suggesting their critical roles in the modulation of lung tumor biology." (PMID 39971779, 2025). "Herein, we confirmed that Gli1 promoted tumor angiogenesis by regulating the crosstalk between lung cancer cells and vascular cells." (PMID 38493151, 2024). "The upregulation of FOXP3 and GLI1 increased the expression lung cancer stem cell markers (e.g., ALDH1A1 and OCT4) and the formation of tumor spheres." (PMID 38674427, 2024). "It is crucial for the activation of the canonical hedgehog (Hh)/Gli1 signaling pathway, which is frequently activated in many cancers, including lung cancer, breast cancer and basal-cell carcinoma." (PMID 38493151, 2024). "We and other groups have previously found that the key transcription factor of the SHH pathway, GLI1, is upregulated and serves as a therapeutic target in lung cancer specimens; however, genetic alterations were rarely detected." (PMID 37149646, 2023). "SOX2 is a downstream target of GLI1, and the GLI1/SOX2 axis contributes to stemness-related EGFR resistance in lung cancer cells." (PMID 37149646, 2023). "We have previously demonstrated that GLI1 is overexpressed in lung cancer specimens and negatively correlated with the prognosis of patients." (PMID 37149646, 2023). "Our data demonstrate that compared with parental cells, paired lung cancer specimens and spheroids exhibit GLI1 overexpression, promoting stem-like cell proliferation." (PMID 37149646, 2023). "As SOX2 was positively modulated by its host gene SOX2OT in a cis-acting manner, we further investigated how SOX2OT interplays with GLI1 and functions in lung cancer stemness." (PMID 37149646, 2023). "RT-qPCR demonstrated that GLI1 or SOX2 overexpression remarkably stimulated the SMO/GLI1/SOX2OT/SOX2 axis in lung cancer cells." (PMID 37149646, 2023).
lung cancer (continued). "Fluorescent in situ staining indicated that enhanced green fluorescent protein (EGFP)-tagged GLI1-overexpressing lung cancer cells had a stronger SOX2OT signal." (PMID 37149646, 2023). "Our data revealed that the GLI1/SOX2OT RNA loop is functionally mediated by m6A modifiers in lung cancer cells." (PMID 37149646, 2023). "We unveiled a novel GLI1/SOX2OT positive loop activated by METTL3/14/IGF2BP2-modified m6A methylation to reinforce the stemness of lung cancer cells." (PMID 37149646, 2023). "SOX2OT has been demonstrated to promote GLI1 expression via histone H3 methylation and acetylation, leading to multiple drug resistance in lung cancer." (PMID 37149646, 2023). "Compared with paired adjacent normal tissues, lung cancer specimens exhibited consistently upregulated GLI1/SOX2OT/METTL3/14/IGF2BP2." (PMID 37149646, 2023). "Spheroid formation assay and the established histogram corroborated that GLI1 repression disrupted METTL3/14/IGF2BP2-stimulated propagation of lung cancer cells." (PMID 37149646, 2023). "Our data unveiled that GLI1 repression reversed METTL3/14/IGF2BP2 overexpression-induced proliferative advantage of lung cancer stem-like cells, suggesting its pivotal role in the whole network." (PMID 37149646, 2023). "We have demonstrated that SOX2 can upregulate GLI1 expression, and SOX2-targeted intervention abolishes GLI1-mediated stemness of lung cancer cells." (PMID 37149646, 2023). "Recent studies have found that SOX2OT promotes GLI1 expression via histone H3 methylation and acetylation, leading to resistance to multiple therapeutic strategies in lung cancer." (PMID 37149646, 2023). "Experimental evidence also shows Gli1 involvement in both small- and non–small-cell lung cancers (SCLC and NSCLC)." (PMID 31137846, 2019). "In conclusion, our studies demonstrate IL-24 effectively suppresses GLI1 and offers a new IL-24-based treatment approach for targeting GLI1 and achieving improved treatment outcomes for lung cancer." (PMID 31783569, 2019). "In the present study, we found that IL-24 inhibits GLI1 expression and induces DNA damage in the lung cancer cells." (PMID 31783569, 2019). "Kaplan–Meier survival curve analysis of 720 lung cancer patients showed that patients with high GLI1 gene expression had a trend towards having low overall survival compared with patients with low GLI1 expression (p = 0.1932)." (PMID 31783569, 2019). "Our study provides evidence that IL-24 treatment induces DNA damage, and reduces GLI1 expression and offers an opportunity for testing IL-24-based therapy for inhibiting GLI1 in lung cancer." (PMID 31783569, 2019). "The present study demonstrates the ability of IL-24 to effectively suppress GLI1 in lung cancer cells and induce DNA damage leading to apoptotic cell death." (PMID 31783569, 2019). "Our lab recently studied upregulated signaling in lung cancer, investigating Gli1’s inverse correlation with E-cadherin; inhibition of the SHh pathway upregulates E-cadherin expression and suppresses lung cancer cell migration." (PMID 29416661, 2018). "Alteration in PTCH expression does not affect oncogenic functions of Hedgehog cascade driven by SHH, SMO, and GLI1 in lung cancer cells." (PMID 28507311, 2017). "Arf6 RNAi efficiently knocked down Arf6 protein levels and reduced Gli1 levels in lung cancer cells." (PMID 28281543, 2017). "Meanwhile, reduction in transcription of Hedgehog cascade members as downstream targets of GLI1 back forwardly further attenuates the SHH signaling in lung cancer cells." (PMID 28507311, 2017). "Activation of Hedgehog/Gli1 signaling promotes the growth, migration, invasion and drug resistance of the lung cancer cells." (PMID 27661123, 2016). "Taken together, these data suggested the tumor suppressive roles of WW45 in lung cancer by inhibiting Hedgehog/Gli1 signaling." (PMID 27661123, 2016). "Taken together, this study demonstrated the suppressive roles of WW45 in lung cancer by inhibiting the Hedgehog/Gli1 signaling." (PMID 27661123, 2016).